IFNG (interferon gamma)
Diseases named in the same sentence as IFNG in open-access papers (continued):
Sharing a sentence is not in itself a finding about the gene and the disease.
cancer (continued). "This coordinated upregulation of MHC-II genes was correlated with higher intratumoral levels of interferon-gamma in HPV+ carcinomas." (PMID 31394808, 2019). "These indicate that cancer immunotherapy acts at least partially through an increase of IFNγ expression." (PMID 30039553, 2018). "Catabolic pro-inflammatory cytokines associated with cancer cachexia include interleukin-6 (IL-6), interleukin-1 beta (IL-1B), tumor necrosis factor alpha (TNF-α), and interferon gamma (IFN-γ)." (PMID 30591621, 2018). "γδ T cells can also directly eliminate cancer cells, produce IFNγ, and enhance CD8 T cell, Th1 T cell, and NK cell activity." (PMID 29686284, 2018). "IFNγ was the most effectively secreted by DCs stimulated with lysate/LPS or TCM/LPS originated from both adherent CRC cell lines whereas the spherical cancer cell-derived factors presented much weaker impact on IFNγ secretion." (PMID 30104575, 2018). "Increased infiltration of CD8+ T cells is associated with high PD-L1 expression likely as a result of an adaptive response where infiltrating CD8+ T cells secrete interferon gamma (IFNγ) that subsequently induces PD-L1 expression on cancer cells." (PMID 30042343, 2018). "The EGFR-mediated suppression of IFNγ/TNFα mediated amplification of the T-cell infiltrate in these cancers bears strong similarities with observations in skin inflammation disorders." (PMID 30192802, 2018). "Interferon-gamma (IFN-γ) is a pleiotropic cytokine that exerts important functions in inflammation, infectious diseases, and cancer." (PMID 30120107, 2018). "Several publications have demonstrated that CTLA‐4 and PD‐1 inhibitors as well as other immune checkpoint blockade therapies result in an increase in IFNγ production, which in turn lead to the elimination of cancer cells." (PMID 30039553, 2018). "Recent studies suggest that inactivation of JAK1 and JAK2 by cancer cells results in resistance to interferon gamma which contributes to checkpoint resistance and immune escape." (PMID 30622524, 2018). "Neutrophil-mediated ADCC toward cancer cells can be enhanced after neutrophil-activation, e.g., by granulocyte-colony stimulating factor (G-CSF) and interferon-γ (IFNγ)." (PMID 30761158, 2018). "Endogenous IDO1 expression is induced in a cancer cell line with interferon gamma and its activity is assessed by measuring kynurenine secreted into the media." (PMID 30112109, 2018). "IFNγ release was used as a measure of redirected T cell activation (using both healthy and cancer patient T cells) against Ag+ cell lines in the presence of antigen-specific ImmTAC molecules." (PMID 30321203, 2018). "Tα1, as an immunomodulator used in cancer therapy, has abilities to induce the activation of DCs and T cells as well as the secretion of interferon-gamma (IFN-γ) and interleukin-2 (IL-2)." (PMID 30109250, 2018). "This process is mainly driven by natural killer (NK) cells that are activated and recruited in response to tissue damage signals, mainly interferon gamma (IFNG) originating from neighbouring cells that are activated by the abnormal growth of cancer cells." (PMID 28193698, 2017). "We cocultured these cells with different cancer lines and analyzed IL-2 and IFNγ secretion as well as activation marker upregulation." (PMID 29085357, 2017). "For example, for the two miRNA pairs that both are members of the miR-15 family (miR-15a/b), the top three possible co-functional targets for the non-cancer diseases are IFNG, MTHFR, RARB, while for cancers are BCL2, CDKN1A and CCND1." (PMID 28340554, 2017). "In a few clinical trials, IFNγ treatment negatively affected patients outcome whereas in other trials, it provided positive effect in cancer patients." (PMID 28512255, 2017). "Further, these studies raise potential concerns regarding the efficacy and safety of IFNγ for the cancer treatment." (PMID 29156701, 2017).
cancer (continued). "There is a large body of evidence to suggest that IFNγ and IL-12 are key determinants of a beneficial immune response in many cancers." (PMID 28327095, 2017). "Using interferon-gamma injection along with DCs, we previously obtained significant clinical responses against small or early stage malignant tumors in dogs." (PMID 29190690, 2017). "Proinflammation cytokines IFNγ and TNFα in serum were lower than normal reference range in 87 of 130 (66.9%) cancer patients after chemo- and/or radiotherapies." (PMID 28529951, 2017). "In cancer patients, peripheral NK cells revealed reduced cytotoxic function, and significantly decreased intracellular IFNγ productions were reported." (PMID 29050291, 2017). "Decreased Natural killer cell activity (NKA) for interferon-gamma production (NKA-IFNγ) has been reported in cancer patients." (PMID 29050291, 2017). "Although IFNγ exhibited antiproliferative, antiangiogenic and pro-apoptotic effects on cancer cells, there is growing reports of its pro-tumorigenic behaviours." (PMID 29156701, 2017). "Our previous studies have shown that treatment with systemic immunostimulatory therapies for cancer results in preferential induction of apoptosis in the CD4 T cell population in an IFNg-dependent mechanism." (PMID 28428882, 2017). "For six of the cancer cell lines IFNγ resulted in increased resistance to NK cells, while for three of them it resulted in increased sensitivity." (PMID 28428785, 2017). "To better understand this variability, we used mass cytometry to evaluate the effect of IFNγ on expression of NK cell ligands by cancer cells." (PMID 28428785, 2017). "A potent anticancer molecule, IL-12, is an interleukin produced by dendritic cells in immune response, and treatment of cancer stimulates the production of interferon-gamma (IFN-γ) and tumor necrosis factor-alpha (TNF-α) from T cells and NK cells." (PMID 27494901, 2016). "Interferon-gamma (IFN-γ) is one of key cytokines that the immune system produce to eradicate cancer cells, so we investigated the function of IFN-γ on CD133+ HCC CSCs in this study." (PMID 26758620, 2016). "The immune inhibitory ligand PD-L1 on cancer cells is upregulated in response to T-cell-derived IFNγ, and engages PD-1 on T-cells, thereby attenuating their effector functions." (PMID 26981247, 2016). "The LN cultures of two out of six cancer patients showed an IFNγ response after stimulation with the AV-SLP conjugates (C879, C896)." (PMID 27564262, 2016). "FIRΔexon2 activated c-myc mRNA expression whereas its levels were negatively correlated with interferon-gamma mRNA level which indicates local immune responses in cancer tissues." (PMID 27756887, 2016). "It has also been proposed that TNFα and IFNγ synergistically inhibit cancer cell growth because IFNγ increases the expression of TNFα receptors." (PMID 27342639, 2016). "The classically activated MΦ1 phenotype, can be induced by interferon γ (IFNγ)/tumor necrosis factor α (TNFα) and exert a cytotoxic effect on cancer cells." (PMID 27231721, 2016). "IFNγ plays a role in diverse biological functions related to host defense and immune regulation in cancer." (PMID 27471636, 2016). "Serial sections of a human cancer tissue array were stained simultaneously using anti-MUC16 or anti-TNFα or anti-IFNγ antibody." (PMID 26918940, 2016). "It has been previously reported that especially for E75 immunization protocols, E75 specific vaccine-induced CTLs failed to recognize HER-2+ tumors and HLA-A2+-HER-2 overexpressing carcinomas, even after IFNγ treatment." (PMID 27891225, 2016). "Specific augmentation, for example, by inducing IFNγ production by Th17 cells, has been shown to be beneficial in many infectious diseases and in some cancers." (PMID 26101460, 2015). "For IDO and PD-L1, cancer cells were in addition stimulated for 48 h with 1,000 U/ml IFNγ, which is known to induce the proteins." (PMID 26510188, 2015).
cancer (continued). "Previous studies have shown that bone marrow-derived MSCs inhibit effector T cell proliferation and IFNγ and TNFα expression and cytotoxicity against cancer cells." (PMID 25984529, 2015). "A summary of expression data shows that—apart from IDO after stimulation of A431, A549, BxPC3 and KATOIII cells with IFNγ—in all cases evasion proteins were expressed in stably transfected CHO cells to a much higher level than in the six cancer cell lines." (PMID 26510188, 2015). "As cited above, the available evidence suggests that IFNγ-producing Th17 cells are beneficial when considering the development of vaccines for infectious diseases and in some cancers." (PMID 26101460, 2015). "The common convergence of cancer immune responses onto patterns of cytotoxic and IFNγ-dominated pathways has been summarised in the concept of an “immune constant of rejection”." (PMID 26362649, 2015). "The authors noted that IL-17+IFNγ+ T cells were more efficient in cancer eradication than IFNγ+ T cells." (PMID 26101460, 2015). "By transcriptional repression, TGF-β secreted by cancer cells can broadly downmodulate effector T cell functions, for instance, by reducing expression of granzymes A and B, perforin and interferon-gamma (IFNγ) upon receptor binding." (PMID 26510188, 2015). "Concurrent IDO and TS downregulation using TS siRNAs numbers 3 or 4, combined with shRNA-mediated reduction of IDO in response to induction with IFNγ, sensitized cancer cells to 5FUdR to a greater degree than TS downregulation alone." (PMID 26579709, 2015). "The potential involvement of IFNγ+ Th17 cells in providing protective immunity to cancer was highlighted in two further studies." (PMID 26101460, 2015). "TLR 7/8 agonists also support the induction of cancer-specific immunity by triggering an innate response characterized by the production of Th1 cytokines (including TNFα, IL-12, and IFNγ) and DC maturation." (PMID 24982761, 2014). "A few of the mechanisms in which cytotoxic T cells work against tumour cells is through the expression of FasL, release of cytolytic granules and secretion of cytokines such as IFNg and TNFa, which induce apoptosis of cancer cells." (PMID 24000152, 2013). "While the qualitative effects of IFNγ were the same in cancer and stellate cells, a quantitative analysis revealed significant differences." (PMID 23284277, 2012). "Together, these results indicate that the cancer cells are less sensitive towards IFNγ than pancreatic stellate cells, and suggest a less efficient activation of STAT1 signaling as a possible molecular explanation." (PMID 21310022, 2011). "SNPs for OAS3, SULF1, DUT, and GTF2H4 were associated with HPV persistence whereas IFNG and EVER1/EVER2 SNPs were associated with progression to CIN3/cancer." (PMID 20084279, 2010). "iNKT cells of cancer patients showed a significant reduction of IFNγ in response to TCR-mediated activation in vitro." (PMID 20593019, 2010). "The ex vivo interferon-gamma (IFN-γ) ELISpot is used extensively as a primary immunogenicity assay to assess T cell-based vaccine candidates in trials for infectious diseases and cancer." (PMID 21179404, 2010). "The optimal conditions for DNA vaccination, therefore, depend on the capacity of electroporation to enhance cellular immunity, especially for cancer vaccines for which IFNγ producing CD8+ T cells are critical." (PMID 20181099, 2010). "Decreased numbers of circulating iNKT cells were accompanied by a decrease in IFNγ production by iNKT cells in advanced prostate cancer and other cancers, concurrent with increased IL-4 production upon re-stimulation in vitro." (PMID 20593019, 2010). "From each region, the single most significant SNPs associated with CIN3/cancer were OAS3 rs12302655, SULF1 rs4737999, IFNG rs11177074, DUT rs3784621, DMC1 rs5757133, GTF2H4 rs2894054, EVER1/EVER2 rs9893818 (p-trends≤0.001)." (PMID 20084279, 2010).
cancer (continued). "HLA-A2 tetramer flow cytometry, IFNγ real time RT-PCR and IFNγ ELISPOT assays are commonly used as surrogate immunological endpoints for cancer immunotherapy." (PMID 18945350, 2008). "Generally speaking, clinical trials investigating the therapeutic potential of IFNγ in cancer had a disappointing outcome." (PMID 18801189, 2008). "After treatment of human carcinoma cells with interferon-gamma (IFN-γ), we observed downregulation of S100A4 both at mRNA and protein levels." (PMID 12799648, 2003). "Our findings across cancer types suggest that deactivation of AR in the TME reflects higher IFNγ signaling activity, which may indicate greater responsiveness to ICB therapy." (PMID 41486951, 2026). "In contrast, high IFNG expression showed no consistent association with improved survival in these cancers." (PMID 41082397, 2026). "Furthermore, the multicellular ecosystem CE9, characterized by effector T cell components and IFNγ signaling, outperformed other cancer ecosystems in predicting better OS and responsiveness to immunotherapy." (PMID 39840456, 2025). "As previously reported in other cancers, IFNγ significantly increased INCR1 levels (third bar)." (PMID 40449595, 2025). "Interestingly, 44As3 exhibited the highest PD-L1 expression among the three cancer cell lines following IFNγ stimulation at 100 ng/mL with levels approximately 15-fold higher than those observed in A549 and T47D cells." (PMID 40001596, 2025). "IFNγ stimulation upregulated PD-L1 expression in all three cancer cell lines." (PMID 40001596, 2025). "We next tested whether a dependence on MBNL for MHC induction following IFNγ stimulation was a common feature of cancer cell lines beyond the B16-F10 model." (PMID 40305509, 2025). "In addition to the IFNγ/JAK/STAT signaling pathway, autophagy has been implicated in the regulation of PD-L1 expression in cancer cells." (PMID 40794185, 2025). "Regarding the sensitivity of cancer cells to T-cell cytotoxicity, the leading positive regulatory processes were necroptosis, IFNγ signaling, and antigen processing and presentation via MHC class I. The leading negative regulatory processes were autophagy and apoptosis." (PMID 39868264, 2025). "It is thus foreseeable that HCMV-mediated IFNγ augmentation might transfer to other pathogens and cancer undergoing treatment with ICB." (PMID 41194666, 2025). "Recent meta-analyses focused on leveraging the statistical power of independent observations have discovered that pre-existing IFNγ pathway mutations in multiple cancer types did not necessitate lack of response to ICB22." (PMID 39746898, 2025). "Additionally, a pan-cancer surge in CD4+ interferon gamma (IFNG+) T follicular helper (Tfh)/Th1 cells, CD8+ Tc17 cells, and mucosal-associated invariant T cells was noted post ICB treatment." (PMID 40054456, 2025). "Some of these molecules may also influence how cancer cells respond to signals from the immune system, especially those related to interferon gamma." (PMID 40724881, 2025). "In contrast, LARS and GAK proteins related to T cell apoptosis and inhibition of IL-12 mediated IFNγ production were linked to high PD-L1 inducing activities in the PDS cultures, in line with a primary cancer niche including T cell infiltration but suppressed cytotoxic activity." (PMID 40240529, 2025). "Thus, Mediator kinase inhibition blocked normal transcriptional responses to IFNγ, consistent with prior studies in Murine Embryonic Fibroblasts (MEFs) and human cancer cells." (PMID 39928031, 2025). "Interferon-gamma (IFN-γ) is a cytokine produced mainly by immune cells and can affect cancer cells by modulating the activity of multiple signaling pathways, including the canonical Janus-activated kinase/signal transducer and activator of transcription (JAK/STAT) cascade." (PMID 40108693, 2025). "Interestingly, lipid-siPDL1s strongly inhibited PD-L1 expression despite cancer cell stimulation by interferon-gamma, which induced the overexpression of PD-L1 genes." (PMID 40001596, 2025).
cancer (continued). "Once triggered, NK cells not only unleash their cytotoxic contents, such as perforin and granzyme B, to induce direct lysis of cancer cells but also rapidly generate chemokines and cytokines like interferon-gamma (IFN-γ), thereby regulating the adaptive immune response." (PMID 40486832, 2025). "It should be noted that other cancer immune escape mechanisms, such as interferon gamma unresponsiveness, may also weaken the treatment efficacy." (PMID 39783790, 2025). "Among them, interferon-gamma (IF-γ) is widely used in cancer therapy; however, recent studies suggest that it may also facilitate metastasis in certain contexts." (PMID 40500394, 2025). "There is ample evidence of HLA-I upregulation in cancer cells by IFNγ,38 which could potentially interfere with CAR NK-92 cell activity." (PMID 40469103, 2025). "Furthermore, the lipid-siPDL1-mediated knockdown effect remained robust even upon stimulation of cancer cells with IFNγ to induce high PD-L1 expression, consistently reducing PD-L1 mRNA levels regardless of its expression levels." (PMID 40001596, 2025). "In addition, CD64-CR T cells exhibit strong immunoregulatory functions since they induce the upregulation of programmed death-ligand 1 (PD-L1) and de novo expression of HLA-DR on cancer cells through the specific production of IFNγ." (PMID 39962623, 2025). "In A549 cancer cells, the conditioned medium from NK-92 cells caused the phosphorylation of STAT1 at Tyr701, as well as the upregulation of the IRF1 and CASP1 proteins, which is consistent with the activity of IFNγ." (PMID 40512405, 2025). "In general, samples from R groups showed more enriched pathways related to inflammasomes, interferon gamma signaling, cancer immunotherapy by PD-1 blockade, T cell receptor and co-stimulatory signaling, IL-12 signaling mediated by STAT4, and co-stimulation by the CD28 family." (PMID 40593467, 2025). "Additionally, it offers proof-of-concept for an innovative approach by targeting IFNγ-mediated pyroptosis or dietary OA supplementation to strengthen the antitumor immunity of γδ-T cells against cancers." (PMID 40603316, 2025). "Another potential beneficial action of TAK‐228 is related to the fact that active T cells and NK cells not only release cytolytic granules containing perforin and granzymes to eliminate cancer cells but also secrete IFNγ, which can trigger apoptosis in cancer cells." (PMID 39258533, 2025). "In the cancer setting, the primary readout is IFNg, secreted by CD8+ T cells and Th1 cells, but inclusion of IL-5 as a second cytokine comes with only minor additional costs in the Fluorospot assay and can provide insights on the presence of epitope specific Th2 cells." (PMID 40103827, 2025). "The observation that the factors secreted by NK-92 cells (mostly IFNγ but possibly other cytokines may have also participated) sensitize cancer cells to apoptosis induced by FAS ligand suggests the potential therapeutic strategy." (PMID 40512405, 2025). "Antitumoral effects may include direct cancer cell killing or the creation of an IFNγ‐rich TME to support antitumor activities of macrophages." (PMID 39931836, 2025). "CBD epigenetically controlled the immunosuppressive effects on T-cells and macrophages, which occurred at the same time as the decreased production of TNF-α and interferon gamma (IFN-γ), in addition to the well-described antiapoptotic mechanisms in cancer cells." (PMID 40243433, 2025). "Furthermore, cancer cells stimulated by interferon-gamma (IFNγ), a cytokine produced by activated T cells, were shown to exhibit enhanced PD-L1 expression." (PMID 40001596, 2025). "IFNγ is one of the main mediators of inflammation in cancer and development of an IFNγ signaling score led to the identification of IFITM3 as both a prognostic biomarker and a direct target of IFNγ with a potential dependency in AML cells lines, i.e., its deletion led to loss of AML cell fitness." (PMID 38418901, 2024).